EPHA3 (EPH receptor A3)
Diseases named in the same sentence as EPHA3 in open-access papers (continued):
Sharing a sentence is not in itself a finding about the gene and the disease.
melanoma (continued). "Functionally, EphA3 overexpression strengthened the proliferation and migration of A375 and A875 cells; on the contrary, miR-3666 mimic weakened two malignant behaviors of melanoma cells; more importantly, the promotion of EphA3 overexpression on melanoma cell growth was blockaded by miR-3666 mimic." (PMID 36578556, 2022). "Undeniably, highly expressed EphA3 was measured in melanoma tissues." (PMID 36578556, 2022). "In addition, induction of ERK1/2 and p38 MAPK pathways offset the positive effect of EphA3 overexpression on melanoma cells." (PMID 36578556, 2022). "Furthermore, miR-3666 mimic compromised the driven melanoma cell proliferation and migration by EphA3 overexpression." (PMID 36578556, 2022). "Hence, we test the ERK1/2 and p38 MAPK signaling pathways in melanoma cell when EphA3 silence." (PMID 36578556, 2022). "Therefore, we speculated that miR-3666/EphA3 might have inhibitory roles in melanoma cells by regulating ERK1/2 and p38 MAPK signaling pathways." (PMID 36578556, 2022). "Finally, a novel antibody-based therapeutic directed against EPHA3, and therapies that induce EPHA3 could sensitize melanoma to antibodies to EPHA3." (PMID 35624662, 2022). "Therefore, EphA3 silence decelerated the cancerogenic potential of melanoma in vivo." (PMID 36578556, 2022). "Therefore, the carcinogenesis of EphA3 on melanoma may be mediated through the activation of ERK1/2 and P38 MAPK signaling pathways." (PMID 36578556, 2022). "Furthermore, irradiation treatment could lessen malignant behaviors of human melanoma cells in parallel with the downregulation of EphA3." (PMID 36578556, 2022). "In mice with syngeneic lung tumours, EphA3 knockdown reduced vasculature and CAF/MSC-like cells in tumours, and inhibited tumour growth, which was confirmed also in a melanoma model." (PMID 37760615, 2023). "Therefore, miR-3666 could sponge EphA3 to exert its inhibitory effect on melanoma malignancy." (PMID 36578556, 2022). "Hence, miR-3666/EphA3 axis may represent a druggable target against melanoma progression." (PMID 36578556, 2022). "EPHA3 and FRS2 are SCNA-affected genes whose products participate in angiogenesis and migration and have the potential to be therapeutic targets for melanoma." (PMID 35157610, 2022). "Western blot analysis further showed that the EphA3-induced upregulation of p-ERK1/2 and p-p38 MAPK was abrogated by miR-3666 mimic in melanoma cells." (PMID 36578556, 2022). "EPHA1, EPHA3 and EPHB6 were contained in regions of copy gain, suggesting their oncogenic role during melanoma progression." (PMID 27095580, 2016). "Our in silico significance and proximity analysis of 28 paired cases (13 WGS and 15 targeted cases) identified known (e.g., BRAF, NRAS, CDKN2A, and GRIN2A) and novel (e.g., EPHA3, GRIN2B, and ASXL3) genes involved in melanoma." (PMID 25393105, 2014). "They highlight the potential of targeting EPHA3, PDGFB signaling, and the modulation of pericyte-CAFs transition as promising strategies for developing novel therapeutic interventions and improving patient outcomes in melanoma." (PMID 38233802, 2024). "Importantly, we also confirm EphA3 expression in similar cell subtypes in the TME of human cancers, including breast, colon and melanoma, by analysis of single-cell RNA sequencing data." (PMID 37760615, 2023). "Additionally, our results emphasize the potential of the EPHA3 and FRS2 gene products, involved in angiogenesis and migration, as possible therapeutic targets in melanoma." (PMID 21494657, 2011).
prostate carcinoma (16 papers, 2015 to 2025). A carcinoma that arises from epithelial cells of the prostate gland. "Conversely, in cancer cells, KHDRBS1 acts as an oncogene, promoting breast cancer metastasis by upregulating EPHA3 gene, and regulating the expression of the androgen receptor splice variant AR-V7 to promote prostate cancer growth." (PMID 38660302, 2024). "High expression of EphA3 was related to lymph node metastasis and advanced stages in colorectal cancer and was associated with higher Gleason score in prostate cancer." (PMID 28465671, 2017). "Cell-to-cell contact of prostate cancer cells through the EphA-ephrin-A interaction suppressed stomatin expression, while knockdown of EphA3/7 or ephrin-A5 increased stomatin expression." (PMID 39377541, 2024). "Markedly, the levels of EPHA3 in the metastatic castration-resistant prostate cancer cell line, C4-2, were much higher than its less aggressive, parental LNCaP cell counter." (PMID 35264657, 2022). "EPHA3 (EPH receptor A3) is upregulated in a variety of human cancers including prostate cancer, and stimulates prostate cancer proliferation and survival in LNCaP cells and mouse xenograft models." (PMID 28035996, 2016). "Previously, a positive correlation between EphA3 expression and Gleason grades in prostate cancer was reported and that EphA3 promotes proliferation and migration of prostate cancer cells was also confirmed." (PMID 25978371, 2015). "Our finding that ephrin-A5 is disassociated from EphA3 and released outside the cell by ADAM10 suggests that ephrin-A5 may have certain diagnostic value in prostate cancer metastasis." (PMID 35551177, 2022). "Having determined the preferential expression of EphA3 on tumour adjacent bone marrow-derived mesenchymal (BMSCs), myeloid and vascular cells, the effect of a chimeric EphA3 agonistic antibody (chIIIA4) was investigated in mouse xenograft models of colon and prostate carcinoma." (PMID 36046842, 2022). "Upregulation of EphA3 in androgen independent prostate cancer cells compared to androgen dependent prostate cancer cells has been observed by microarray analysis, and a tentative relationship between mutant AMP-activated protein kinase (AMPK) and upregulation of EphA3 mRNA has been proposed." (PMID 29682554, 2018). "However, whether EPHA3 promotes or suppresses prostate cancer progression requires further investigation." (PMID 35264657, 2022). "Collectively, EPHA3 may have a critical role in advancing human prostate cancer." (PMID 35264657, 2022). "To determine the mechanism by which STK4/MST1 signaling controls EPHA3 expression, we first assessed the abundance of the Ephrin A (EphA) and Ephrin B (EphB) receptor subtypes and their respective ligands in the well-characterized human prostate cancer cell lines LNCaP, C4-2, 22Rv1, and PC3." (PMID 35264657, 2022). "IIIA4 treatment of EphA3-negative prostate cancer cell xenografts disrupted newly emerging tumour vessels and surrounding stroma, in line with EphA3 expression on these tissues in the TME." (PMID 36830852, 2023).
breast carcinoma (15 papers, 2010 to 2025). "Single cell RNA sequencing analysis of multiple human tumour types confirmed EphA3 expression in CAFs, including in breast cancer, where EphA3 was particularly prominent in perivascular- and myofibroblast-like CAFs." (PMID 37760615, 2023). "KHDRBS1 also promotes the progression of human breast cancer by up-regulating the activation of a surface antigen (EphA3), probably leading to the development of metastasis." (PMID 33213024, 2020). "However, very little is known regarding the potential role of EphA3 in the pathophysiology of breast cancer, including TNBC." (PMID 34021125, 2021). "Besides ABCB1 and EPHA3, we found that the annotation genes for the top 10 circRNAs in docetaxel-resistant breast cancer cells are involved in neuronal development, synaptic vesicle trafficking, histone-binding, and maintaining epithelial function via the PI3K/AKT signaling pathways." (PMID 34055636, 2021). "A previous report in breast cancer had shown that EphA3 could regulate αDG." (PMID 31463571, 2019). "In breast cancer, EphA3 was identified on both cancer cells (upregulated by RAGE signalling), and on CAFs, and its activity promoted invasion, which was blocked by a specific EphA3 inhibitor." (PMID 39780187, 2025). "In breast cancer, ART increased EPHA8, EPHA10, EFNA2 and reduced EPHA3, EPHA7, and EFNA3." (PMID 38630320, 2024). "Some non-canonical BMP4 target genes identified in this study, such as EPHA3 and SORL1, have been implicated in the progression of breast cancer." (PMID 38689334, 2024). "hRNase 1 induced phosphorylation of EphA4, but not of EphA3 or EphA5, and activation of phospholipase C-γ (PLCγ), a downstream signaling molecule of EphA430, in BT-549 basal-like breast cancer cells." (PMID 33986289, 2021).
colorectal cancer (12 papers, 2010 to 2024). A primary or metastatic malignant neoplasm that affects the colon or rectum. "Elevated EphA3 expression is linked to poor prognosis in several malignancies including gastric cancer, colorectal cancer, and hepatocellular carcinoma." (PMID 38952552, 2024). "High expression levels of EphA3 are associated with poor prognosis in gastric cancer, colorectal cancer, and hepatocellular carcinoma." (PMID 34221956, 2021). "Here, we used a tissue microarray containing triplicate tumor samples from 159 patients with Dukes C colorectal cancer to investigate possible associations between EPHA3 levels and survival of colorectal cancer patients." (PMID 28169277, 2017). "According to recent studies, altered EPHA3 expression is associated with gastric and colorectal cancers, and CNVs in the EPHA3 region have been found to be associated with haematologic malignancies." (PMID 23967248, 2013). "Recent studies have found gene mutations in the kinase domain of EphA3 in colorectal cancer cells." (PMID 28194092, 2017). "Based on these genetic data, and the known importance of EPH signaling in colorectal cancer, EPHA3 inactivation would be expected to significantly contribute to the progression of colorectal tumors." (PMID 28169277, 2017). "Here we used inducible isogenic cell line systems, animal models and large human tumor collections to investigate the role of EPHA3 during colorectal cancer progression." (PMID 28169277, 2017). "In conclusion, we have investigated here the functional role of EPHA3 on the oncogenic process of colorectal cancer." (PMID 28169277, 2017). "To investigate the functional role of EPHA3 in colorectal cancer, we engineered two cell line systems with doxycycline-dependent inducible EPHA3 expression." (PMID 28169277, 2017). "Nevertheless, mutations in the kinase domain of EPHA3 was reported in 5% of colorectal cancer cell lines and EPHA3 was listed among the top 3 cancer genes in a large-scale screening for somatic mutations in colorectal cancer." (PMID 25193853, 2014). "Similarly, for colorectal cancer patients, higher expression of Ephexin1 and EphA2 correlated to worse survival rates, and lower expression of EphA3 correlated to worse survival rates." (PMID 35668076, 2022). "Eph receptor A3 (EPHA3) plays a tumor suppressive role in esophageal squamous cell carcinoma, and the loss of its expression is related to lymph node metastasis and TNM staging of colorectal cancer." (PMID 36106335, 2022). "Here, we assessed the levels of EPHA3 in the tumors of a cohort of 159 patients with locally advanced (Dukes C) colorectal cancer by immunohistochemistry with a rabbit polyclonal antibody that specifically detects human EPHA3 on formalin-fixed, paraffin embedded samples." (PMID 28169277, 2017). "Similarly, EphA3 expression was downregulated in colorectal cancer cells, possibly via the same mechanism, and suggestive of the fact that EphA3 may possess tumour-suppressing abilities." (PMID 33430066, 2021). "In addition, immunohistochemical analysis of EPHA3 tumor levels did not reveal associations with survival or clinicopathological features of colorectal cancer patients." (PMID 28169277, 2017). "The intestinal tumors observed in the Apcmin/+ and AOM animal models used do not metastasize and are therefore not ideally suited to investigate the role of EPHA3 on the metastatic dissemination of colorectal cancer cells." (PMID 28169277, 2017). "However, the role of EPHA3 in colorectal cancer has not been thoroughly investigated." (PMID 28169277, 2017).
gastric cancer (9 papers, 2017 to 2024). A primary or metastatic malignant neoplasm involving the stomach. "Anti-EPHA2 monoclonal antibody DS-8895a has been tested on esophageal and gastric cancer patients and EPHA3 antibody IIIA4 (Ifabotuzumab/KB004) on GBM cases and patients with hematologic malignancies." (PMID 34445116, 2021). "We aim to elucidate the clinicopathological factors and prognostic importance of EphA3 role in gastric cancer." (PMID 28465671, 2017). "Kaplan-Meier curves were plotted for OS of low and high EphA3 expression in gastric cancer patients." (PMID 28465671, 2017). "We analyzed the clinicopathological factors and prognostic relevance of EphA3 expression in gastric cancer." (PMID 28465671, 2017). "Our study has suggested prospective investigation for the possibility of correlation between EphA3 and liver recurrence in gastric cancer." (PMID 28465671, 2017). "Our study suggests that high expression of EphA3 may play crucial roles in tumor development, metastasis, and survival in gastric cancer." (PMID 28465671, 2017). "However, the role and mechanism of EPHA3 in gastric cancer is still not well understood." (PMID 28465671, 2017). "Although EphA3 failed to reach the statistical value for independent prognostic factor, our study showed that EphA3 overexpression was associated with depth of tumor, lymph node metastasis, stage, distant metastasis and recurrence of gastric cancer." (PMID 28465671, 2017). "However the role and mechanism of EphA3 in gastric cancer is not well understood." (PMID 28465671, 2017). "EPHA1, EPHA2, EPHA3, EPHA5, EPHB2 and EPHB4 expression has been reported as 2-fold higher in stromal cells isolated from gastric cancer tissues compared with normal gastric tissue stromal cells." (PMID 34445116, 2021). "For example, EPHA3 interacts with the receptors for ephrin, promoting the migration of colorectal epithelial cells, whereas IL1RL1 is involved with the IL-33 receptor attracting gastric cancer cells." (PMID 39554905, 2024). "This present study showed that EphA3 overexpression was associated with depth of tumor, lymph node metastasis, stage, distant recurrence, liver recurrence and poorer RFS of gastric cancer." (PMID 28465671, 2017).
hepatocellular carcinoma (9 papers, 2017 to 2024). A malignant tumor that arises from hepatocytes. "Furthermore, high EphA3 expression is associated with metastasis, advanced stages and worse survival in gastric, colorectal and hepatocellular carcinoma." (PMID 37434266, 2023). "High EphA3 expression was also linked to increased tumour volume, grade, and metastases and a much worse prognosis in hepatocellular carcinoma (HCC)." (PMID 36830852, 2023). "EPHA3 was found to be related to cancer occurrence and development, such as lung, colorectal, and hepatocellular cancers." (PMID 36765579, 2023). "In hepatocellular carcinoma, high EphA3 expression was related with tumor size, tumor grade, metastasis, venous invasion." (PMID 28465671, 2017).
multiple myeloma (8 papers, 2017 to 2023). "EPHA3 plays a crucial role in the angiogenesis of multiple myeloma (MM), and the specific targeting of EPHA3 using a monoclonal antibody has an impact on primary bone marrow endothelial cells (ECs) of MM patients." (PMID 37627077, 2023). "For example, EphA3 upregulation stimulates angiogenesis in multiple myeloma and attenuates cancer progression." (PMID 36578556, 2022). "More specifically, EPHA3, which is elevated in both bone marrow endothelial cells and plasma cells from Multiple Myeloma patients, promotes their adhesion, migration, angiogenesis and invasion." (PMID 33634116, 2021). "This study investigates the role of ephrin receptor A3 (EphA3) in the angiogenesis of Multiple Myeloma (MM) and the effects of a selective target of EphA3 by a specific monoclonal antibody on primary bone marrow endothelial cells (ECs) of MM patients." (PMID 28415715, 2017). "The literature has suggested that EPHA3 functions as a proangiogenic factor in multiple myelomas." (PMID 31262977, 2019). "In addition to its role in T cell lymphomas, EphA3 also plays a role in multiple myeloma angiogenesis suggesting that an effective anti-EphA3 therapy could be potentially utilized for treatment of both T and B cell malignancies." (PMID 31333644, 2019). "Therefore EphA3 may be an appropriate target for the treatment of Multiple Myeloma." (PMID 33634116, 2021). "Moreover, EPHA3 is a viable anti-leukaemic target, with the success of an activating monoclonal antibody (IIIA4), targeted payload delivery, or RNAi-mediated EPHA3 knockdown in models of multiple myeloma and pre-B-ALL, as well as in human myeloid malignancies." (PMID 34359759, 2021).
acute lymphoblastic leukemia (6 papers, 2015 to 2025). Leukemia with an acute onset, characterized by the presence of lymphoblasts in the bone marrow and the peripheral blood. "For example, dasatinib is used in the activation of EphA3 via mediating role of the ABL1 protein kinase domain in lymphoblastic leukemia, and PORCN is considered suitable for the palmitoleation of mammalian Wnts to treat ovarian cancer." (PMID 36139498, 2022). "EphA3 was originally identified in the LK63 pre-B acute lymphoblastic leukemia (ALL) cell line and further investigations revealed its expression in other leukemic cell lines." (PMID 26083390, 2015). "There are several oncogenic proteins such as EPHA3 and RSPO1, RSPO2, and RSPO3, which are overexpressed in lung adenocarcinomas and lymphoblastic leukemia and define the patient’s survival rates." (PMID 36139498, 2022).